PFN1 (profilin 1)
Diseases named in the same sentence as PFN1 in open-access papers (continued):
Sharing a sentence is not in itself a finding about the gene and the disease.
Hypertension (7 papers, 2010 to 2024). The presence of chronic increased pressure in the systemic arterial system. "Furthermore, in line with our results transgenic overexpression of profilin-1 targeted to VSMCs caused vascular hypertrophy and hypertension in mice, and this was associated with significant increases in phospho-ERK1/2, phospho-JNK, and phospho-ROCK II kinase in mouse aortas." (PMID 21049052, 2010). "In mice overexpressing PFN1 in blood vessels, hypertension was induced along with vascular wall thickening." (PMID 37543598, 2023). "Profilin-1 gene may represent a new therapeutic target in the treatment of vascular diseases such as hypertension." (PMID 22693641, 2012). "To determine the mechanism by which PFN1 enhanced HESC decidualization, we utilized a Human Hypertension array to identify factors in HESC regulated by PFN1." (PMID 28821715, 2017).
pancreatic cancer (7 papers, 2014 to 2025). "To explore the mechanisms underlying the inhibition of pancreatic cancer cell growth mediated by Pfn1, we used mass spectrometry to identify the potential Pfn1-interacting proteins." (PMID 25103363, 2014). "Quantitative real-time PCR was used to analyze Pfn1 expression profiles of 40 paired pancreatic cancer tissues." (PMID 25103363, 2014). "AKT2 and MCM7 were overexpressed, and CAMTA2 and PFN1 were underexpressed in pancreatic cancer tissues than in morphologically normal operative margin tissues." (PMID 25502777, 2014). "Cell proliferation assays revealed that overexpression of Pfn1 significantly attenuated pancreatic cancer cell proliferation (P < 0.05)." (PMID 25103363, 2014). "To further evaluate the role of Pfn1 in tumor proliferation, we used two pancreatic cancer cells with high lymph node and liver metastatic properties, BxPC-3-LN and SW1990-HM separately." (PMID 25103363, 2014). "The expressions of GLUT1 and LDHA were inhibited remarkably after Pfn1 upregulation, thereby contributing to glycolytic pathways that are crucial for pancreatic cancer progression." (PMID 25103363, 2014). "According to our previous study, PFN1 enhanced the apoptosis of pancreatic cancer cells through a mitochondrial pathway." (PMID 25103363, 2014). "A recent study by our group also demonstrated that overexpression of Pfn1 in pancreatic cancer cells facilitated apoptosis and repressed autophagy induced by irradiation." (PMID 25103363, 2014). "Our data suggest that Pfn1 is a tumor suppressor in pancreatic cancer that acts via a novel mechanism of regulating the SIRT3-HIF1α axis, independently of its cytoskeleton-related activity." (PMID 25103363, 2014). "Profilin 1 was identified as a secreted protein from tumor masses at progressive stage in skin fibromas, in oral cancer saliva proteome and also in pancreatic cancer secretome." (PMID 25084196, 2014). "To elucidate the clinical relevance of Pfn1 in pancreatic cancer, we analyzed a cohort of 72 pancreatic cancer specimens using IHC with a Pfn1-specific antibody." (PMID 25103363, 2014). "The reversal of the Pfn1 overexpression phenotype by Pfn1 knockdown (KD) further demonstrated that Pfn1 exerts a growth-suppressive function in human pancreatic cancer." (PMID 25103363, 2014). "In this study, tissue microarray analysis demonstrated that Pfn1 was significantly downregulated in pancreatic cancer, which was in consistent with previous observations from a proteomic study." (PMID 25103363, 2014). "However, in carcinogenesis, contradictory observations have been reported, as PFN1 suppressed tumorigenicity in pancreatic cancer, while promoted gastric cancer progression." (PMID 27683119, 2016). "Furthermore, survival analysis revealed that downregulation of Pfn1 correlated with shorter survival times for pancreatic cancer patients." (PMID 25103363, 2014). "In conclusion, we described a novel regulatory mechanism whereby pancreatic cancer proliferation is inhibited by the interaction of Pfn1 and SIRT3 to destabilize HIF1α, which results in reduced expression of HIF1α target genes that coordinate aerobic glucose consumption." (PMID 25103363, 2014). "Previously, we showed that up-regulation of Pfn1 could induce apoptosis of pancreatic cancer cells through a mitochondrial pathway." (PMID 25103363, 2014). "Our clinical findings suggested that Pfn1 might play a role in the tumor differentiation and progression of pancreatic cancer." (PMID 25103363, 2014). "Our recent studies suggested that Pfn1 facilitates apoptosis in pancreatic cancer cells." (PMID 25103363, 2014). "However, the mechanisms underlying this effect of Pfn1 in pancreatic cancer have not yet been delineated." (PMID 25103363, 2014).
pancreatic cancer (continued). "Additionally, we examined HIF1α expression in mouse specimens and found that the proportions and staining signals for HIF1α were substantially lower than those in control tumors, suggesting that the increased HIF1α expression might result from Pfn1 downregulation in pancreatic cancer." (PMID 25103363, 2014). "In this study, we validated Pfn1 as a tumor-suppressor in pancreatic cancer, and identified a novel mechanism of PFN1 regulation of the SIRT3- HIF1α axis, independent of its cytoskeleton-related activity." (PMID 25103363, 2014). "Immunohistochemistry (IHC) and western blotting were then used to examine the expression of Pfn1 in pancreatic cancer tissues and corresponding adjacent non-cancerous tissues." (PMID 25103363, 2014). "Restoration of Pfn1 in pancreatic cancer cells with low endogenous Pfn1 expression resulted in a nontumorigenic phenotype, suggesting that Pfn1 may be a negative regulator of pancreatic cancer progression." (PMID 25103363, 2014).
endothelial dysfunction (6 papers, 2010 to 2022). In vascular diseases, endothelial dysfunction is a systemic pathological state of the endothelium (the inner lining of blood vessels) and can be broadly defined as an imbalance between vasodilating and vasoconstricting substances produced by (or acting on) the endothelium. "Serum profilin 1 was independently associated with endothelial dysfunction, cardiovascular events and survival in patients with chronic kidney disease." (PMID 33163494, 2020). "It was recently reported that profilin-1 overexpression triggered indicators of endothelial dysfunction and attenuated the expression of profilin-1 conferred protection from AS in vivo." (PMID 24090212, 2013). "Profilin-1 was increased in the endothelium of diabetic animals, and its overexpression in cultured ECs triggered indicators of endothelial dysfunction (apoptosis, ICAM-1 expression, decreased NO signaling)." (PMID 21049052, 2010). "However, I3R (40 μM) demonstrated the best effect in improving endothelial dysfunction in AGEs-induced EA.hy926 cells, followed by C3G, and A7G was the weakest, as evidenced by the molecular docking results of flavonoids with profilin-1." (PMID 35268006, 2022). "In endothelial cells, UCA1 formed a ternary complex with USP14 and PFN1, prolonged the half-life of the PFN1 protein, and subsequently activated the RhoA/ROCK pathway to produce excess ROS and induce endothelial dysfunction." (PMID 36160709, 2022).
gastric cancer (6 papers, 2014 to 2025). A primary or metastatic malignant neoplasm involving the stomach. "Conversely, PFN1 negatively regulates cell migration in various cancers, including osteoblast, breast, and gastric cancer cells." (PMID 40149625, 2025). "Silencing profilin-1 inhibits the proliferation and metastasis of gastric cancer cells by inducing cell cycle arrest." (PMID 34234838, 2021). "Abnormal expression of profilin-1 is related to gastric cancer tumor invasion, lymph node metastasis, and tumor node metastasis (TNM) staging." (PMID 34234838, 2021). "However, overexpression of profilin 1 was observed in renal cell carcinoma and gastric cancer." (PMID 33163494, 2020). "Studies also link PFN1 to migration regulation in non-small-cell lung carcinoma (NSCLC) and gastric cancer cells." (PMID 40149625, 2025). "For example, studies have found that 14-3-3β and profilin-1 can be used to predict LNM of gastric cancer and 14-3-3β may become an independent prognostic marker for gastric cancer." (PMID 32127941, 2020).
Huntington disease (6 papers, 2012 to 2025). Huntington disease (HD) is a rare neurodegenerative disorder of the central nervous system characterized by unwanted choreatic movements, behavioral and psychiatric disturbances and dementia. "Dysregulation of or mutations in the PFN1 gene have also been implicated in Fragile X syndrome, spinal muscular atrophy, Huntington’s disease, Parkinson’s disease, and adrenoleukodystrophy." (PMID 39769211, 2024). "As an essential protein for all eukaryotic cells, PFN1 has now been linked to several human diseases such as Huntington disease and cancer." (PMID 22479341, 2012). "Meanwhile, in Huntington’s disease (HD), PFN1 maintains huntingtin (Htt) in a soluble state and reduces its aggregation and toxicity by interacting with proline-rich domains (PRD) of Htt." (PMID 40409555, 2025). "Our prior work identified PFN1 as an inhibitor of huntingtin aggregation, suggesting a role in the pathogenesis of Huntington Disease (HD)." (PMID 22479341, 2012). "Finally, based on pathway, three genes were associated with cytoskeletal regulation by Rho GTPase pathway (ACTB, PFN1 and CFL1) while two genes were associated each with glycolysis (GAPDH and PGK1) and Huntington disease (GAPDH and ACTB)." (PMID 34681026, 2021).
colorectal cancer (5 papers, 2020 to 2025). A primary or metastatic malignant neoplasm that affects the colon or rectum. "Studies have found that HLA-F-AS1 promotes colorectal cancer progression via regulation of the miR-330-3p/PFN1 axis and that expression levels of HLA-F are negatively correlated with the prognosis of brain glioma." (PMID 40251569, 2025). "For example, HLA-F-AS1 expression has been shown to influence the production and migration of macrophages via intermediates such as microRNA (miRNA) and profilin 1 in colorectal cancer." (PMID 35935961, 2022). "For instance, HLA-F-AS1 promotes colorectal cancer progression by sponging miR-330-3p to upregulate PFN1 expression." (PMID 33154765, 2020). "The effects of Pfn1 remain relatively understudied in the area of colorectal cancer." (PMID 38730628, 2024).
familial amyotrophic lateral sclerosis (5 papers, 2015 to 2024). An instance of amyotrophic lateral sclerosis that is caused by an inherited modification of the individual's genome. "Human profilin-1 is a novel protein associated with a recently discovered form of familial amyotrophic lateral sclerosis." (PMID 26227615, 2015). "However, mutations in PFN1 are also linked to hereditary amyotrophic lateral sclerosis, resulting in a broad range of cellular pathologies which cannot be explained by its primary function as a cytosolic actin assembly factor." (PMID 39026010, 2024). "In addition, HuR and Pfn1 are both involved in familial amyotrophic lateral sclerosis." (PMID 32098764, 2020).
lung cancer (5 papers, 2018 to 2023). A malignant neoplasm involving the lung. "The mechanisms underlying the roles of PFN1 in metastasis were different from cancer to cancer and those in lung cancer are still unclear." (PMID 35586060, 2022). "PFN1 induced tumour metastasis by promoting microvesicle secretion in non‐small cell lung cancer, and increased expression of PFN1 was found in DCs." (PMID 36822595, 2023). "An in vitro study analyzed the effects of PL in lung cancer cell lines with a modulated expression of profilin-1 (PFN1), one of the actin-binding proteins (ABPs), which plays a critical role in the regulation of cellular migration." (PMID 36046754, 2021). "Collectively, these studies implied that downregulation of Pfn1 can promote the early steps of BC metastasis (similarly, another group demonstrated increased dissemination of lung cancer cells upon LOF of Pfn114)." (PMID 30318519, 2018). "Research related to ABPs and lung cancer has mainly focused on twinfilin-1 (TWF1) and fascin-1 and on the relationships between VASP, profilin-1, and cofilin-1." (PMID 34194957, 2021).
chronic periodontitis (4 papers, 2011 to 2023). A chronic inflammatory process that affects the tissues that surround and support the teeth. "However, there is only a limited amount of literature that explains their roles in periodontitis, highlighting an area of potential research, in particular differentially increased expression of profilin-1 within UWS/SWS samples from CP." (PMID 37834046, 2023). "In addition, other GCF proteins were also identified previously and confirmed in the current investigation as alpha 1 antitrypsin, cofilin-1, profilin 1, cathelicidin antimicrobial peptide, and heat shock protein in chronic periodontitis subjects." (PMID 24098404, 2013). "In accordance with a previous report, myeloperoxidase, myosin 9, annexin A3, profilin-1, L-plastin (plastin-2/LCP1), S100A8, and S100A9 were detected at higher levels in chronic periodontitis patients compared to healthy individuals." (PMID 21794177, 2011).
frontotemporal dementia (4 papers, 2013 to 2023). Frontotemporal dementia (FTD) comprises a group of neurodegenerative disorders, characterized by progressive changes in behavior, executive dysfunction and language impairment, as a result of degeneration of the medial prefrontal and frontoinsular cortices. "Intriguingly, a significant number of genes involved in the pathogenesis of PDB (namely SQSTM1, VCP, PFN1, and OPTN) have been also associated with neurodegenerative disorders (e.g., ALS or frontotemporal dementia) suggesting shared pathophysiological mechanisms." (PMID 36035996, 2022).
hepatocellular carcinoma (4 papers, 2016 to 2022). A malignant tumor that arises from hepatocytes. "According to research findings, the overexpression of PFN1 significantly inhibits the proliferation, migration, and invasion of hepatocellular carcinoma cells." (PMID 36291059, 2022). "Gt-K has also been found to exert anti-metastatic effects in hepatocellular carcinoma, through an up-regulation of the actin-binding protein profilin 1 (PFN1)." (PMID 34586597, 2021).
liver cancer (4 papers, 2016 to 2024). An epithelial or non-epithelial malignant neoplasm that arises from the liver. "Of the remaining two PFN1 positive liver cancer cell lines, one was reported to be of endothelial origin (SK-HEP-1)." (PMID 27494863, 2016). "The results demonstrated that the expression of FCER1G, PFN1, ACTG1, PABPC1, CALM1, and RPS8 was significantly upregulated in the liver cancer cells, whereas KLRB1, LDB2, and FYN exhibited the opposite trend." (PMID 37397471, 2023). "Compared to the non-cancerous liver cell lines, the three liver cancer cell lines had barely detectable levels of PFN1 protein expression." (PMID 27494863, 2016). "An early study has shown that there is a decrease in PFN1 protein expression in liver cancer specimens, without referring to any of the clinical stages." (PMID 27494863, 2016). "We also examined PFN1 expression levels in five liver cancer lines and three non-cancerous liver cell lines." (PMID 27494863, 2016). "To date, a potential role of PFN1 in early liver cancer progression has not been reported." (PMID 30769793, 2019).
Paget’s disease of bone (4 papers, 2023 to 2025). "A novel osteolytic disorder due to PFN1 mutation was discovered recently as early-onset Paget’s disease of bone (PDB)." (PMID 37895866, 2023). "A heterozygous deletion of the PFN1 gene has been detected in patients with Paget’s disease of bone, a chronic progressive bone disorder of late onset." (PMID 39769211, 2024).
triple-negative breast carcinoma (4 papers, 2021 to 2024). An invasive breast carcinoma which is negative for expression of estrogen receptor (ER), progesterone receptor (PR), and human epidermal growth factor receptor 2 (HER2). "For example, overexpression of PFN1 is associated with PSMC1 in the MDA-MB-231 triple-negative breast cancer cell line and may involve multiple mechanisms for cancer progression." (PMID 34329194, 2021). "To overcome this, we used PLP-conjugated agarose beads to purify and enrich endogenous Pfn1 from the triple-negative breast cancer MDA-MB-231 cell line." (PMID 34235154, 2021). "Additionally, it has been demonstrated that in triple negative breast cancer cell lines, overexpression of PFN1 suppresses AKT (serine-threonine kinase) activation via upregulation of PTEN (phosphatase and tensin homolog), indicating the tumor-suppressive character of PFN1 gene." (PMID 34681026, 2021).
breast tumour (3 papers, 2018 to 2022). "As modifications of PFN1 levels were previously shown to impact PTEN levels in breast tumour cells, we evaluated the protein levels of PTEN in PFN1 patient lymphoblasts by Western blot analysis." (PMID 35628504, 2022). "Lower Pfn1 expression is correlated with lower nuclear grade of breast tumours and longer relapse-free survival of BC patients." (PMID 30318519, 2018).
COVID-19 (3 papers, 2021 to 2024). A disease caused by infection with severe acute respiratory syndrome coronavirus 2. "Another protein, PFN1 overexpression, implicated in vascular hyperpermeability and vascular hypertrophy, can perhaps explain the aberrant physiology of COVID-19 patients." (PMID 33995121, 2021). "Similarly, we found significantly reduced levels of proteins of the actin cytoskeleton network amongst COVID-19 convalescents, e.g. PFN1 and CFL1 (cluster A), partially contrasting what had been found for the acute phase." (PMID 38396092, 2024). "As PFN1 expression is altered by SARS-CoV-2 infection, it can be identified as a biomarker to detect COVID-19." (PMID 37007947, 2023). "Further, PFN1 is an important player in activation of viral transcription and airway hyperresponsiveness, and it is known to be downregulated in non-severe COVID-19 patients." (PMID 38396092, 2024).
fragile X syndrome (3 papers, 2021 to 2025). A genetic syndrome caused by mutations in the FMR1 gene which is responsible for the expression of the fragile X mental retardation 1 protein. "Moreover, PFN1 expression is reduced in FMRP-depleted mice, a classical disease model related to Fragile-X syndrome (FXS), and overexpression of PFN1 can significantly rescue the developmental defects in this disease model." (PMID 40409555, 2025).
glioblastoma (3 papers, 2020 to 2025). The most malignant astrocytic tumor (WHO grade IV). "For example, PFN1 has been found to be involved in tumor angiogenesis in glioblastoma and was also found to be associated with poor prognosis in our study (HR > 1)." (PMID 32848578, 2020).